INS (insulin)
Diseases named in the same sentence as INS in open-access papers (continued):
Sharing a sentence is not in itself a finding about the gene and the disease.
chronic pancreatitis (39 papers, 2011 to 2026). A chronic inflammatory process causing damage and fibrosis of the pancreatic parenchyma. "Impaired GIP-induced insulin secretion is further observed in the setting of chronic pancreatitis, and in individuals with mutations in HNF1α (MODY3 diabetes)." (PMID 40024571, 2025). "Available data suggest that MNPs can reduce insulin synthesis by damaging β-cells and increase the risk of chronic pancreatitis." (PMID 41303677, 2025). "Habitual drinking will clinically cause chronic pancreatitis, resulting in impaired insulin secretion from pancreatic beta cells." (PMID 38200049, 2024). "Heavy alcohol consumption has also been linked to chronic pancreatitis and liver injury, with decreased insulin secretion and insulin resistance." (PMID 37098575, 2023). "Additionally, very heavy alcohol consumption and smoking are well known risk factors for chronic pancreatitis, with alcohol, cocaine, and opioid use linked to presentations of acute pancreatitis and altered insulin secretion profiles." (PMID 34912300, 2021). "Fourth, although we excluded participants with chronic pancreatitis, recurrent attacks of AP might have affected the association between the indices of insulin sensitivity and IPFD." (PMID 32967240, 2020). "Treatment of hereditary pancreatitis is the same as the management of other causes of chronic pancreatitis and primarily involves administration of analgesia, pancreatic enzymes, fat-soluble vitamins, sometimes insulin and avoidance of alcohol and tobacco, as well as a low-fat diet." (PMID 29515728, 2017). "Thus, Toxoplasmosis has also been implicated as a possible contributing factor in chronic pancreatitis also the inadequacy of insulin secretion, sustained blood and increased urine sugar." (PMID 24578838, 2013). "The pooled insulin independence rate was 34%, with higher rates for non-chronic pancreatitis indications (68%) versus chronic pancreatitis (33%)." (PMID 41508796, 2026). "Autologous islet transplantation is particularly beneficial for patients undergoing total pancreatectomy (TP) for chronic pancreatitis, as it can significantly improve their quality of life by maintaining insulin independence or reducing insulin demand." (PMID 40747090, 2025). "The endocrine results of our total cohort of chronic pancreatitis operations are comparable to prior studies examining the impact of pancreatic surgery on glycemic control and insulin requirements." (PMID 40869642, 2025). "Diseases such as chronic pancreatitis can affect the pancreas’s ability to store and secrete both zinc and insulin." (PMID 39839287, 2024). "The authors found a weak relationship between stimulated insulin, C-peptide levels and glycemic measures with the isolated islet mass in adult patients with chronic pancreatitis undergoing TPIAT." (PMID 34067286, 2021). "Five chronic pancreatitis patients underwent spleen-preserving total pancreatectomy and intrasplenic islet autotransplantation, of whom two achieved insulin independence for over a year." (PMID 29735923, 2018). "Islet cell autotransplants in patients undergoing TP for chronic pancreatitis have shown to have durable function and extended insulin-independence rates, despite a lower beta-cell mass." (PMID 22966212, 2012). "At the University of Minnesota, in 18 patients surveyed under the age of 18 suffering from chronic pancreatitis who underwent pancreatectomy and islet autotransplantation, only 7 were on narcotics, and 10 were insulin independent at 1 year." (PMID 22013505, 2011). "A diagnosis of pancreatic diabetes caused by chronic pancreatitis was made based on decreased insulin secretion, normal insulin resistance, and negative anti-glutamic acid decarboxylase antibody." (PMID 33614349, 2021). "It has been accepted that injury to islet cells in chronic pancreatitis results in insulin deficiency; however, normal or elevated fasting plasma insulin levels in patients with chronic pancreatitis do not support the expected findings." (PMID 33472655, 2021).
chronic pancreatitis (continued). "Hence, in order to describe the impact of surgery for chronic pancreatitis on Type 3c diabetes outcomes, we aim to compare preoperative versus postoperative glycemic control and insulin dependency after both PPS, TP, and TPIAT operations for chronic pancreatitis." (PMID 40869642, 2025). "Male sex, chronic pancreatitis, non-gallstone aetiology of AP, critical care admission, and organ support requirement, including parenteral nutrition, were identified by univariate analysis as significant risk factors for medication- and insulin-controlled DM." (PMID 36515672, 2022). "Given that chronic pancreatitis is a risk factor for PDAC and that an inflammatory environment can directly promote tumor initiation, we employed here TD protocols P2 and a third protocol (P3, based on a combination of IGF-1, SCF and transferrin) for the generation of insulin-expressing cells." (PMID 34572891, 2021). "As the plasma insulin AUCs in the WBKDF-NS group was significantly lower than that in the Wistar-NS group, the reduced insulin secretory function in the WBKDF rats may be due to pancreatic β-cell dysfunction associated with chronic pancreatitis." (PMID 29744365, 2018). "We found surgery for chronic pancreatitis to result in good endocrine outcomes, for no patients in our analysis suffered from postoperative hypoglycemic events, and the majority remained free from insulin at one-year follow-up." (PMID 40869642, 2025).
Hypomagnesemia (39 papers, 2009 to 2026). An abnormally decreased magnesium concentration in the blood. "Insulin and metformin usage was associated with hyponatremia, hypochloremia, hypocalcemia, and hypomagnesemia." (PMID 39449943, 2024). "Insulin upregulates TRPM6 activity; thus, patients with lower insulin receptor activity are more susceptible to hypomagnesemia." (PMID 38511086, 2024). "Hypomagnesemia is thought to have detrimental effects on beta-cell proliferation and mass, affecting insulin production and secretion." (PMID 39202546, 2024). "Although we confirmed this positive effect of acute hypomagnesemia on insulin secretion, it is notable that diabetic patients usually experience chronic hypomagnesemia." (PMID 37443824, 2023). "Some clinical epidemiological studies suggest that hypomagnesemia accounts for declines in insulin secretion in patients with type 2 diabetes (T2D); however, the results of various experimental studies do not support this notion." (PMID 37443824, 2023). "Several studies have revealed an association between hypomagnesemia and type 2 DM and NODAT, while oral Mg2+ supplementation increases insulin sensitivity and metabolic control in type 2 DM patients, but not in those with NODAT." (PMID 33919913, 2021). "It has been reported that hypomagnesemia can lead to a defective activity of tyrosine kinase and can modify insulin sensitivity by influencing the activity of the insulin receptor after binding or by influencing the intracellular signaling and processing." (PMID 32085495, 2020). "Perhaps, hypomagnesemia lead to inadequate beta-cell compensation for the decrease in insulin sensitivity." (PMID 31419950, 2019). "Second, hypomagnesemia inhibits glucose utilization in both basal and insulin-stimulated states." (PMID 32185236, 2020). "Apart from diabetic complications and the mortality rate, hypomagnesemia could influence both insulin secretion and insulin action." (PMID 22291997, 2012). "Even though we found that short-term Mg2+ deficiency does not impair insulin secretion, this finding might not contravene the relationship between hypomagnesemia and T2D since diabetic patients usually experience chronic hypomagnesemia." (PMID 37443824, 2023). "Hypomagnesemia is also a risk factor for PTDM, and its mechanism might be as follows: hypomagnesemia can reduce the activity of insulin tyrosine kinase, affect the synthesis and secretion of insulin, and cause hyperglycemia after transplantation." (PMID 36843576, 2023). "Our results do not support an important role for hypomagnesemia on insulin sensitivity or development of PTDM after kidney transplantation." (PMID 39911868, 2025). "This indicates that it is not enough to improve metabolic control with insulin or oral hypoglycaemic agents: it is also important to reverse hypomagnesemia." (PMID 22192330, 2011). "Hence, in contrast to current thinking, our findings strongly suggest that long-term hypomagnesemia does not negatively impact the metabolic phenotype, insulin secretion, and β-cell function." (PMID 37443824, 2023).
pancreatic neuroendocrine tumor (39 papers, 1987 to 2026). Pancreatic endocrine tumor, also known as pancreatic neuroendocrine tumor (PNET), describes a group of endocrine tumors originating in the pancreas that are usually indolent and benign, but may have the potential to be malignant. "Tumour-associated hypoglycaemia due to insulin secretion from non-islet-cell tumours is also possible, but very rare." (PMID 24683485, 2014). "Evidence suggests that high-molecular-weight IGF-2, secreted by non-islet cell tumors of mesenchymal origin, interacts with insulin and IGF-1 receptors, as well as binding proteins, to induce the expression of hexokinase and other glycolytic enzymes." (PMID 40568267, 2025). "A well-differentiated intermediate grade 2 pancreatic neuroendocrine tumor producing insulin was confirmed on histopathology." (PMID 34583764, 2021). "Our patient had GCA and concomitant LA, thus suggesting the possibility of ectopic secretion of insulin from non-islet-cell tumors." (PMID 29166433, 2019). "Previous studies have reported that insulin-secreting non-islet-cell tumors can originate in any germ layer, and that all of them have a single tissue origin." (PMID 29166433, 2019). "Hypoglycemia can be induced by tumors, including pancreatic tumors that secrete insulin, and also by non-islet cell tumors that secrete IGFs." (PMID 31842913, 2019). "Pathological examination showed all three tumors were pancreatic neuroendocrine tumors; the tumor cells in the largest mass were strongly immunoreactive for insulin." (PMID 27864816, 2016). "In 2011, Filippella reported a case of a diabetic patient with a pancreatic endocrine tumour co-secreting insulin and ACTH." (PMID 24683485, 2014). "We report a case of a female patient who presented with primary hyperparathyroidism (pHPT) and a GHRH- and insulin cosecreting pancreatic NET (pNET) and genetically confirmed multiple endocrine neoplasia type 1 (MEN1), within an undiagnosed family with various MEN1-related NETs." (PMID 42007244, 2026). "Differential diagnosis led to detection of an insulin-secreting neuroendocrine tumor of the pancreas; thus, a paraneoplastic origin of SPS was hypothesized." (PMID 40355790, 2025). "The second major class of pancreatic cancer is pancreatic neuroendocrine tumors (also termed islet cell tumors), which arise from cells that make up the endocrine gland of the pancreas, which secretes insulin, gastrin, and glucagon into the serum to regulate glucose uptake and metabolism." (PMID 37371782, 2023). "Thus far, ectopic secretion of insulin has been reported in only a few non-islet-cell tumors, and all of these had a single tissue origin in different germ layers." (PMID 29166433, 2019). "It was interesting that NAP1L1 affected the proliferation of pancreatic neuroendocrine tumor cells via modulation of p57 (Kip2) promoter methylation, whether affected insulin secretion or regulated blood glucose, however, the mechanism had not been elucidated." (PMID 30299268, 2018). "Conversely, in spite of their larger pancreatic neuroendocrine tumors, RT2 AB6F1 expressed only two-fold more serum insulin than wildtype AB6F1 mice." (PMID 30796198, 2019). "Our patient had a nonfunctioning pancreatic endocrine tumor at diagnosis and developed multiple hepatic metastases, which later became functional for insulin secretion approximately 6 years after the initial diagnosis." (PMID 26425568, 2013). "RT2 AB6F1 mice, on the other hand, may develop some other kind of pancreatic neuroendocrine tumor that does not express insulin." (PMID 30796198, 2019). "In addition to this, we speculate that the molecular mechanism through which non-islet-cell tumors secrete insulin probably differs from that of islet cell tumors." (PMID 29166433, 2019).
pancreatic neuroendocrine tumor (continued). "In addition, the insulin-regulated PI3K-Akt-mTOR pathway plays an important role in the regulation of islet cell proliferation, and this pathway is hyperactivated in human non-functional pancreatic neuroendocrine tumors (PanNETs)." (PMID 37679316, 2023).
periodontal disease (39 papers, 2010 to 2025). "Inflammation is a common link between periodontal diseases and diabetes, and further research is needed to elucidate how inflammatory periodontal diseases impact insulin resistance, glycemic control, and the risk of other diabetic complications." (PMID 40418274, 2025). "This correlation endorses the pathogenic links existing between periodontal diseases and cellular resistance to insulin." (PMID 34840527, 2021). "Insulin patients are normally on longer-term therapy, which is a risk factor for non-compliance with self-care behaviors and poor glycemic and periodontal disease control." (PMID 33822810, 2021). "The development of diabetes mellitus contributes to the exacerbation of periodontal disease and ligature-induced periodontal disease in turn has been linked to decreased insulin sensitivity in rats." (PMID 24478766, 2014). "Periodontal disease is a risk factor for cardiovascular disease, generally manifested by increased inflammation and potential changes in hypercoagulability and insulin resistance." (PMID 39035441, 2024). "In addition to periodontal disease, P.gingivalis is also associated with systemic diseases, of which insulin resistance is an important pathological basis." (PMID 37520442, 2023). "Furthermore, periodontal disease causes gingival inflammation, and the resulting secretion of inflammatory substances into blood circulation interferes with the ability of insulin to reduce blood glucose levels." (PMID 31164111, 2019). "A possible pathological link has been proposed between HCV infection and the development of periodontal disease based on two main pathways – insulin resistance and chronic inflammatory process in the liver." (PMID 40490688, 2025). "This refined analysis pinpoints the role of inflammation, insulin resistance, body fat, and dietary habits in the pathway from periodontal disease to LFC accumulation." (PMID 40270511, 2025). "Studies have shown the importance of controlling periodontal disease on improving glycemic control, highlighted by a decrease in insulin demand and a decrease in HbA1c levels." (PMID 39597869, 2024). "Our results suggest that the metabolic (insulin) patterns differ in these two forms of periodontal disease, with CP showing some statistically significant results." (PMID 36651310, 2023). "On the other hand, the chronic release of pro-inflammatory cytokines in active periodontal disease reduces insulin action." (PMID 37851692, 2023). "We show that specific taxa associated with periodontal disease (the MIP) in subgingival plaque are also significantly correlated with blood pressure, fasting insulin, and HOMA-IR." (PMID 35444197, 2022). "Subject to additional evidence, it will be beneficial to prevent and treat periodontal disease in non-insulin-dependent patients in order to maximize the therapeutic outcomes of lifestyle interventions." (PMID 29548317, 2018). "Poor metabolic control of glucose levels and insulin requirements may follow from chronic infection in periodontal disease." (PMID 40217896, 2025). "Moreover, we have identified a spectrum of factors—encompassing inflammation, body fat, diet habit, insulin resistance —that act as intermediaries in the relationship between periodontal disease and SLD." (PMID 40270511, 2025). "The treatment of periodontal disease aimed at reducing inflammation may lead to the restoration of insulin sensitivity over time, resulting in improved metabolic control." (PMID 39597869, 2024). "However, resistance training promoted an improvement in insulin sensitivity in rats with periodontal disease." (PMID 35029853, 2022). "In a recent study that evaluated the relationship between oral health, insulin resistance and resistance training in rats, it was observed that periodontal disease promoted a decrease in insulin sensitivity, due to the release of inflammatory mediators, such as the tumor necrosis factor-α (TNF -α)." (PMID 35029853, 2022).
periodontal disease (continued). "The authors attributed their results to the inflammatory nature of both CKD and periodontal disease, which may result in peripheral insulin resistance, leading to high glucose levels in the blood." (PMID 35340502, 2022). "Participants using combined therapy of oral hypoglycemics and insulin in this study were twice more likely to have periodontal disease than those who were using insulin alone, and the chances were thirteen percent when compared to those who were using oral hypoglycemics." (PMID 36942143, 2022). "From these data it might be reasonable to control and manage periodontal disease in non-insulin-dependent patients in order to maximize the therapeutic outcome of lifestyle interventions." (PMID 29548317, 2018). "Smaller studies could identify the effect of the successful treatment of periodontal disease on inflammatory markers, insulin sensitivity and markers of coagulation and oxidative stress." (PMID 27846870, 2016). "Finally, being a secondary data analysis, certain variables of interest were not available, such as tooth brushing history and frequency, oral hygiene, and other variables related to T2DM management (insulin and oral antidiabetic medication) which can influence the severity of periodontal disease." (PMID 39588166, 2024). "A previous study from our group showed that β-glucan increased insulin secretion in diabetic animals with periodontal disease and reduced glucose levels in diabetic animals with or without periodontal disease." (PMID 28906456, 2017).